KRAS (KRas proto-oncogene, GTPase)
Diseases named in the same sentence as KRAS in open-access papers (continued):
Sharing a sentence is not in itself a finding about the gene and the disease.
cancer (continued). "Indeed, as demonstrated here and elsewhere, cancer cells carrying oncogenic KRAS are less able to cope with the ER stress caused by the disruption of the N-glycosyations as compared with KRASwt cells, which undergo UPR-mediated apoptosis." (PMID 33670598, 2021). "Thus, using this NGS panel in cfDNA of mCRC patients and following ACMG and AMP guidelines, we were able to frequently identify cancer-associated variants with strong clinical significance in relevant genes, such as KRAS and PIK3CA." (PMID 34640513, 2021). "The KRAS proto-oncogene and its associated pathways are frequently mutated in cancer." (PMID 34706236, 2021). "One interpretation is that oncogenic G12 mutations may be superior to Q61 mutations in some manner, which is interesting insofar as G12 mutations are more common in KRAS than Q61 mutations in human cancers." (PMID 33998997, 2021). "In addition, a mRNA-based cancer vaccine (V941) targeting the most commonly occurring KRAS mutations (G12D, G12V, and G12C) is under clinical study (NCT03948763)." (PMID 34301278, 2021). "Additionally, survivors acquired KRAS mutations not present in their parents, suggesting that glucose deprivation can drive the acquisition of (KRAS) pathway mutations in human cancer cells." (PMID 33925206, 2021). "Cancers harbouring KRAS mutations comprise a very heterogeneous selection." (PMID 34064232, 2021). "The role of the genes identified in this study in the carcinogenesis and progression of CRC with KRAS G12 mutations may be a modulation of the cancer phenotype, the nature of which should be elucidated in future studies." (PMID 33982211, 2021). "Researchers have explored additional explanations and have found that the mesenchymal cancer cell phenotype, which has been previously associated with a lower reliance on KRas for tumorigenic processes, instead relies on PI3K signaling, mediating resistance to G12C inhibitors." (PMID 34680208, 2021). "KRAS is a common mutated oncogene in human cancers, such as pancreatic, colon, and lung cancer." (PMID 33796026, 2021). "Each have been linked to KRAS, suggesting that KRAS plays a key role in hypoxia in cancer." (PMID 33691728, 2021). "Thus, the advancement of existing options and development of novel therapeutic strategies for KRAS-mutated cancers heavily relies on further understanding the context in which KRAS mutant signaling occurs." (PMID 34573384, 2021). "Activating mutations in KRAS are present in 25% of human cancers." (PMID 34680229, 2021). "SBS8, of unknown etiology, had a substantial probability of causing several of the KRAS alleles, particularly G12V, across all four cancers." (PMID 33753749, 2021). "Additionally, the scientific literature commonly estimates 30–33% of all cancers have a mutation in either KRAS, NRAS, or HRAS50–52." (PMID 34645806, 2021). "Interestingly, DR5 has been shown to positively regulate cell invasion and metastasis in KRAS-mutated cancer cells while suppressing invasion and metastasis in HRAS mutant animal models, albeit with an undefined underlying mechanism." (PMID 33810241, 2021). "Its persistent activation due to KRAS mutation contributes to cancer progression." (PMID 33777798, 2021). "Efforts channelled in this direction, might pave the way in solving the long-standing challenge of targeting the KRAS mutations in cancers." (PMID 34781949, 2021).
cancer (continued). "KRAS is the predominant mutated RAS gene in human cancer and the initiating genetic event for PDAC." (PMID 33505218, 2021). "Gain-of-function variants in KRAS are commonly found in human cancers." (PMID 33472608, 2021). "One potential explanation for this result may be due to the intrinsic radio-resistance specific to KRAS mutated cell lines, which has been extensively researched in various other types of cancers where KRAS mutations are also prevalent." (PMID 33803606, 2021). "However, due to the difficulty in targeting Ras, contemporary efforts focused on targeting other proteins in the MAPK-ERK pathway despite Ras, particularly KRas, having high rates of oncogenic mutations in multiple cancers, especially PAC." (PMID 34680208, 2021). "Since KRAS mutation was observed in 40–50% of CRCs, KRAS mutations may be good targets of neoantigen-based cancer vaccine or TCR-engineered T cell therapies." (PMID 34638288, 2021). "Despite advances in our understanding of the structure, function, and cellular signaling pathways that underlie KRAS-mutant cancer development, KRAS targeting remains a therapeutic challenge, which demands further understanding of the biological and biochemical functions of KRAS." (PMID 33917906, 2021). "Immune evasion is a hallmark of KRAS-driven cancers, but the underlying causes remain unresolved." (PMID 33674596, 2021). "Importantly, high HIF-1α levels and, to some extent, high Gal3 expression are associated with a poorer survival of human cancer patients, in particular in association with mutant KRAS, which emphasizes the need for suitable potent inhibitors." (PMID 33672199, 2021). "In addition to KRAS mutation, KRAS amplification also contribute for disease progression in cancers including PDAC." (PMID 34805167, 2021). "We hypothesized that the constitutively active form of mutated KRAS, highly associated with Rho family GTPases, promotes the production of exosomes from cancer cells, owing to the membrane relatedness and vesicular trafficking association." (PMID 33466836, 2021). "KRAS is the most frequently mutated oncogene in human cancer." (PMID 33674596, 2021). "Furthermore, we revealed that NTRK3 promoter hypermethylation is highly associated with MSI and KRAS mutation that is known as response biomarkers for cancer treatment and have conflicting predictive value for survival." (PMID 33593392, 2021). "The most commonly mutated isoform of RAS among all cancer subtypes is KRAS." (PMID 33802849, 2021). "Previous studies showed that DMF is preferentially cytotoxic to cancer cells with KRAS mutations." (PMID 33692690, 2021). "KRAS, an oncogene mutated in approximately 25% of human cancers, regulates NRF2 signaling." (PMID 34830482, 2021). "Fourth, cancer cells that harbor KRAS mutations are particularly sensitive to suppression of ERH." (PMID 33809701, 2021). "Noteworthy, the scenario of KRAS mutated cancer is extremely heterogeneous and complex." (PMID 33777798, 2021). "SMYD3 silencing may reduce the progression of advanced cancer rendering SMYD3 a potential therapeutic target for cancer patients with KRAS mutations." (PMID 34335697, 2021). "In addition, several somatic variants in established cancer driver genes were identified, including driver genes of colorectal tumourigenesis, such as KRAS and FBXW7." (PMID 34843512, 2021). "Analysis of 55,308 cancers registered in a public database revealed a significant trend toward co-occurrence of mutations in KRAS and SMAD4 (p < 0.0001; see Section 4.4 for details), indicating a potential synergistic role of these mutations in cancer survival and progression." (PMID 35008475, 2021). "This compound series is limited to cancers harboring G12C mutations, however, a cyclic peptide, KRpep-2d with a preference for G12D mutations has been identified that binds in a similar pocket showing that biologics can also probe pockets in KRAS." (PMID 34193876, 2021).
cancer (continued). "Importantly, there was substantial variability of the alleles found at these hotspots across the four KRAS-driven cancers." (PMID 33753749, 2021). "Since PDAC has the highest incidence of KRAS mutation among all types of cancers, the inhibition of mutant KRAS-driven pathways could be a good strategy to prevent this cancer." (PMID 33546421, 2021). "Based on these preliminary preclinical results, BI 1701963, the second representative of SOS1 inhibitors, is being tested, alone and in combination with MEK inhibitor trametinib, in a phase I clinical trial in cancer patients carrying pan-KRAS mutations (NCT04111458)." (PMID 33777798, 2021). "In addition, we need to fully understand why acquired KRAS mutations are more prominent in certain cancer types." (PMID 33801965, 2021). "Importantly, we found significantly less KRAS mutations in incident cancers than previous studies analyzing prevalent CRC in LS." (PMID 34206061, 2021). "KRAS mutation is one of the most common mutation in human cancer." (PMID 34123854, 2021). "One of the most promising strategies to block KRAS-mutant oncogenesis is the concept of synthetic lethality, in which suppressed or inhibited genes or proteins cause cell death only in the presence of a cancer-specific alteration." (PMID 32948832, 2021). "They identified a de-novo KRAS Y96D mutation affecting the switch-II pocket, able to interfere with key protein-drug interactions and confer resistance to KRAS-G12C KIs in engineered and patient-derived KRAS G12C cancer models." (PMID 34064232, 2021). "Therefore, LKB1 expression directly affects the global m6A levels via ALKBH5 in KRAS-mutated cancer cells." (PMID 34016959, 2021). "High IL-10 levels were associated with a worse prognosis in patients with KRAS mutated cancers." (PMID 33777798, 2021). "Remarkably, the KRAS gene is the most frequently mutated oncogene in human cancer." (PMID 34336638, 2021). "Representing a central hub in resistance to RAF and MEK inhibition, targeting YAP1 could represent a combination therapy in KRAS mutated cancers." (PMID 33777798, 2021). "Lastly, the presence of a KRAS mutation highlights that SMC may represent another potential cancer precursor in the pancreas." (PMID 33511431, 2021). "A number of co-occurring mutations may contribute to adaptive resistance across KRAS mutant cancers." (PMID 34064232, 2021). "However, KRAS is often mutated leading to its hyperactivation in cancer, thereby mediating activation of multiple effectors/pathways like the PI3K/AKT and MAPK pathways, which both, can increase glycolysis and are involved in lipid biosynthesis." (PMID 33691728, 2021). "The combination of MIP-assisted capture and mass spectrometry was used to distinguish between WT and mutated forms of KRAS, and we successfully tested this approach in three distinct biological systems demonstrating the utility of this approach for the diagnosis of cancer." (PMID 34854867, 2021). "KRAS has mutations in a variety of cancers, among which the mutation rate of pancreatic cancer is as high as 90%, that of colon cancer and lung cancer (mostly non-small cell lung cancer) account for 30–50% and 19% respectively, and cholangiocarcinoma accounts for about 26%." (PMID 34249939, 2021). "KRAS is the most commonly mutated oncogene in human cancers." (PMID 34032581, 2021). "KRAS is mutated in 25% of all of the cancer cases, and is associated with poor disease prognosis." (PMID 34298594, 2021). "Additionally, triple targeted nanoparticles featuring the CXCR4 antagonist for cancer stromal blockade action, as well as anti-miR-210 and siRNA targeting mutated KRAS were developed." (PMID 34683931, 2021). "KRAS, an oncogene, is frequently activated by mutations in many cancers." (PMID 34172714, 2021). "For example, KRAS is known to affect metabolism when mutated on different types of cancers." (PMID 32850411, 2020).
cancer (continued). "In addition to tissue based isoform specificity the frequency of different KRAS missense mutations can vary in different cancer types." (PMID 32552660, 2020). "However, in right sided cancers MetS, defined with BMI ≥29 as cut-off of high waist circumference, was significantly associated with KRAS status (OR 6.000, 95% CI 1.501–23.991, p = 0.007)." (PMID 32594310, 2020). "Two cases of KRAS wild-type in cancer gene panel testing showed KRAS mutations on viewing the BAM file (KRAS G12V, allele frequency 1%; KRAS G12R, allele frequency 1%), and these findings were concordant with the results of KRAS mutation analysis using residual materials." (PMID 31999789, 2020). "Future research will explore other KRAS mutations and inhibitors of cancer development." (PMID 32486141, 2020). "Anti‐KRAS could be utilized as a good strategy to develop new methods for treating cancers with MB21D2 overexpression or its Q311E recurrent mutation." (PMID 32979859, 2020). "Equally, 50% of non recto-sigmoid cancers exhibited KRAS mutation." (PMID 32594310, 2020). "The KRAS mutations have been an obstacle to identify therapeutic targets in cancer treatment." (PMID 32244355, 2020). "Drawing from our previous data, we investigated whether FMD + vitamin C would sensitize KRAS-mutated cancer cells to the pro-oxidant action of chemotherapy in vivo, possibly by increasing cellular oxidative stress." (PMID 32393788, 2020). "Thus, an amplification loop between IL-1β and mutated-KRAS seems to increase cancer progression and drug resistance." (PMID 32635472, 2020). "KRAS mutations are amongst the most pervasive genetic alterations in human cancer." (PMID 32678871, 2020). "It is of interest that within one cancer type, KRAS mutation may occur in a given specific histotype." (PMID 32725342, 2020). "Therefore, KRAS-targeted degradation is an attractive therapeutic strategy for cancers with KRAS mutations, and not limited to any specific codon change." (PMID 32591521, 2020). "It has been suggested that the type of mutations in KRAS may have an influence on its ability to transform and the drug responses of cancer patients." (PMID 33122197, 2020). "Mutations in the KRAS isozyme are the most frequent of all cancers with RAS mutations." (PMID 33073260, 2020). "Additionally, GSEA analysis in HMCLs upon ST3GAL6-AS1 KD evidenced that low ST3GAL6-AS1 expression levels are associated with gene set downregulation in cancer cell lines carrying an oncogenic form of KRAS." (PMID 32218309, 2020). "Indeed, some studies report that cancer cell lines which harbor many different mutations, as well as specific cancer mutations such as KRas, can alter breast epithelial calcium signaling responses." (PMID 33569087, 2020). "Over 30% of cancers are driven by mutant Ras proteins, thereinto, one method called catalog of somatic mutations in cancer (COSMIC) confirms that HRas (3%) are the least frequently mutated Ras isoforms in human cancers, where KRas (86%) are the predominantly mutated isoforms followed by NRas (11%)." (PMID 33266473, 2020). "KRAS is a gene that has the potential to cause cancer when it is mutated i.e. it is an oncogene." (PMID 32300895, 2020). "Given the high incidence of oncogenic KRas mutations in human cancers, and the ability of calmodulin to modulate oncogenic KRas activity, targeting calmodulin in these settings may unravel novel treatment options." (PMID 32456244, 2020). "For example, KRAS-mutated cancer cells could induce myeloid-derived suppressor cells trafficking by secreting granulocyte macrophages and colony-stimulating factor (GM-CSF), which inhibits the behavior of CD8+ T cells." (PMID 33316775, 2020). "Thus, establishing a screening platform to target cancers with KRAS mutations is expected to have significant implications." (PMID 32678871, 2020).
cancer (continued). "This may be due to T cell exhaustion induced by vaccination by upregulating checkpoint molecules, such as PD-1, or neoantigen editing that allow cancer cells to adapt to the driver mutations such as KRAS G12 mutations." (PMID 33298945, 2020). "Among the three paralogs, KRAS is the most frequently mutated protein in cancers, followed by NRAS." (PMID 33187149, 2020). "In the multivariable analysis (Model 1), the positivity of the D-marker panel remained an independent risk factor for cancer progression after adjusting for cancer differentiation, KRAS mutation, and BRAF mutation, and the adjusted hazard ratio (HR) (95% CI) was 1.52 (1.09 to 2.11)." (PMID 32532105, 2020). "The specificity of KRAS mutant cfDNA detection in pancreatic exocrine secretions may also be higher than blood, as mutation detected in the blood may develop from cancers at sites other than the pancreas." (PMID 32825312, 2020). "In addition, the alternated cancer‐related hallmark pathway was also found, such as KRAS signaling up, epithelial–mesenchymal transition and phosphatidylinositol‐3‐kinase (PI3K)/Akt and the mammalian target of rapamycin (mTOR) signaling." (PMID 32686362, 2020). "We discuss the preclinical work on KRAS-induced inflammation and immune modulation in the context of currently ongoing clinical trials targeting cancer entities that carry KRAS mutations and strategies to overcome the oncogene-induced effects on the immune system." (PMID 33116132, 2020). "The extensive mutation rate of the KRAS oncogene has played detrimental roles in cancer initiation, propagation and maintenance and thus could be highlighted as a therapeutic target for specific treatment." (PMID 32270277, 2020). "Thereby, cancers with KRAS mutations experience constitutively elevated signaling via KRAS effector pathways such as activation of the phosphatidylinositol 3 kinase (PI3) kinase pathway via direct interaction of KRAS with the catalytic PI3K subunit p110α62." (PMID 32194994, 2020). "Altogether, these data suggest that oncogenic KRAS mutations are functionally different and could contribute to the biological and clinical heterogeneity of cancers." (PMID 32708575, 2020). "KRAS mutation is one of the most common genetic changes in human cancers." (PMID 32641995, 2020). "Taken together, these observations suggest that miR181ab1 plays an important role in human KRAS-mutated oncogenesis and that its ablation could cooperate with targeted agents to improve therapeutic efficacy in KRAS-mutated cancers." (PMID 31874105, 2020). "Thus, targeting the typical hot-spot mutations in KRAS is an attractive approach in KRAS mutated cancer treatment." (PMID 32903495, 2020). "Interestingly, YAP1 has been implicated in both oncogenic KRAS-dependent and -independent cancer-promoting activities 11-14, suggesting it plays a critical role across a wide range of cancers." (PMID 32292505, 2020). "Our study shows a proof of concept for the development of pan-KRAS specific degraders as therapeutics that could be implemented in any cancer with KRAS mutations." (PMID 32591521, 2020). "TG01 is the first cancer immunotherapy targeting KRAS oncogenic mutations." (PMID 32063605, 2020). "Similarly, another independent study revealed KRAS mutations to be common determinants of acquired resistance in CRC cancer patients." (PMID 33144898, 2020). "In support of our interpretation, we reported here that young pancreata that are known to be more susceptible to cancer initiation than adult pancreata express only the prenylated form of KRAS, contrary to adult pancreata, which also present unprenylated forms." (PMID 32887255, 2020).